S100A9 (S100 calcium binding protein A9)
Diseases named in the same sentence as S100A9 in open-access papers (continued):
Sharing a sentence is not in itself a finding about the gene and the disease.
psoriasis (continued). "Of particular note, S100A9 is associated with most diseases, including arthritis, lupus, IBD, psoriasis, and dermatitis." (PMID 27089880, 2016). "The suppression of SCCA1 has been demonstrated to inhibit tumour growth, HEC expression is increased in tumours and S100A9 has been found to be up-regulated in psoriasis patients displaying keratinocyte hyperproliferation and altered differentiation." (PMID 16001974, 2005). "Additionally, si-Yap1 significantly decreased the expression of psoriasis-related genes, including S100a7, S100a8, and S100a9." (PMID 40108109, 2025). "The activation and activity of S100A8 and S100A9 is an indicator of psoriasis and may indicate the response of the immune system to psoriasis." (PMID 40540498, 2025). "Furthermore, the deletion of the gene coding for S100A9 led to an attenuation of psoriasis-like disease in a murine model." (PMID 38256115, 2024). "However, recent evidence has observed that lower epidermal levels of S100A9 in mice lead to more severe psoriasis skin lesions." (PMID 38256115, 2024). "Furthermore, both necroptosis and ferroptosis in keratinocytes have been implicated in psoriasis and IMQ-induced psoriasis-like dermatitis, through the release of inflammatory cytokines such as S100A8, S100A9, HMGB1, IL-33, IL-1β, and IL-6." (PMID 38429278, 2024). "Additionally, the expression of alarmins S100a8 and S100a9, which have been considered as reliable biomarkers for monitoring inflammatory disease activity in psoriasis, was also decreased." (PMID 38891893, 2024). "Recently, S100A8 and S100A9 were proven to contribute to psoriatic skin inflammation and could be a biomarker of psoriasis severity." (PMID 38429278, 2024). "Furthermore, a study showed that S100A8 and S100A9 can regulate psoriasis by inhibiting production of the IL-17 A and IL-17 F." (PMID 39095779, 2024). "The mechanisms of S100A8 and S100A9 in psoriasis were revealed to some degree in previous studies." (PMID 37891988, 2023). "Several studies support the important role of S100A9 in psoriasis." (PMID 37653756, 2023). "In addition, serum S100A8 and S100A9 levels are increased in psoriasis and positively correlated with PASI score, indicating that their production is positively correlated with disease development in psoriasis." (PMID 37891988, 2023). "In common, these models of psoriasis showed psoriatic characteristics, such as epidermal hyperproliferation, acanthosis, parakeratosis, and altered expression of psoriatic genes, including S100A9 and hBD2, similar to the results of the present study." (PMID 35745784, 2022). "Serum levels of S100A8/S100A9 correlate with disease activity in psoriasis patients." (PMID 35812457, 2022). "Consistently, deletion of S100A9 reduces psoriasis-like inflammation in mice." (PMID 35812457, 2022). "To understand the molecular mechanism of N4BP1 in the regulation of neutrophil infiltration, we examined the mRNA level of several key genes involved in inflammation including TNFa, IL-23, IL-17, CXCL1, CCL20, S100A8, and S100A9 in psoriasis skin from N4BP1 KO and WT mice." (PMID 33990547, 2021). "S100A9 can be an effective target for the treatment of psoriasis." (PMID 34134787, 2021). "CXCL9, SPRR1B, TGM6 and S100A9 may be potential targets for the diagnosis and treatment of psoriasis." (PMID 34134787, 2021). "Parallel with the expression of S100A8 and S100A9 IMQ-treated mice developed psoriasis features like erythema, scaling, thickening of skin, parakeratosis, acanthosis of the epidermis, signs of hyperproliferation of keratinocytes, and increased numbers of basal keratinocytes." (PMID 33643287, 2020). "Serum levels of S100A8/S100A9 show a close correlation to disease activity in psoriasis patients." (PMID 33643287, 2020).
psoriasis (continued). "In line with previous reports, we found a high expression of both proteins S100A8 and S100A9 in a murine model of IMQ-induced psoriasis which confirms also data obtained from human psoriatic lesions showing a strong increase of S100A8 and S100A9 expression in keratinocytes." (PMID 33643287, 2020). "S100A8 and S100A9 have manifold inflammatory activities, which may amplify disease activity in psoriasis." (PMID 33643287, 2020). "Hence, potential roles for S100A8 and S100A9 both as treatment targets and biomarkers for psoriasis disease severity have been proposed." (PMID 30865695, 2019). "For instance, S100A8 and S100A9 form a complex called calprotectin that aggravates psoriasis by regulating expression of the C3 complement factor, while hBD-2 promotes chemotaxis of various leukocytes in a C-C chemokine receptor (CCR) 2- and CCR6-dependent manner." (PMID 30918469, 2019). "Both SERPINB3 and S100A9 are modulators of inflammatory response, highly inducible in keratinocytes, and have been found to be de-regulated in inflammatory skin diseases such as venous ulcers, psoriasis, atopic dermatitis, and skin cancer." (PMID 26318001, 2015). "Moreover, S100A8/S100A9 are involved in interactions between keratinocytes and other immune cells and contribute to the pathogenesis of psoriasis by generating specific psoriatic milieu." (PMID 24901012, 2014). "Genes S100A8 and S100A9, frequently co-expressed and forming a heterodimer, belong to a multigenic and multifunctional family of calcium-binding proteins, that has been identified in several inflammatory skin conditions such as psoriasis, atopy, and cancer." (PMID 21556364, 2011). "Furthermore, S100A8 and S100A9 may inhibit psoriasis by prohibiting the synthesis of IL-17A and IL17-F." (PMID 40540498, 2025). "Therefore, we explored whether S100A8 and S100A9 participate in the function of GSDME in keratinocytes for promoting psoriasis-like dermatitis." (PMID 38429278, 2024). "In addition, by confirming that AOA significantly reduced the expression of psoriasis-associated antimicrobial peptides (Defb4, Lcn2, S100a7, and S100a9), we revealed that AOA ameliorated psoriasis-related symptoms and had anti-inflammatory effects in a mouse model of psoriasis." (PMID 37649889, 2023). "After complement components and immunoglobulin chains, S100A8 was the first protein that, as an alarmin, plays a key role in the development of inflammation; moreover, it has been suggested that S100/S100A9 heterodimer may represent a good therapeutic target in psoriasis and psoriatic arthritis." (PMID 36700196, 2022). "Furthermore, IL-1β stimulation of NHEKs was found to induce upregulation of the mRNA and protein levels of pro-inflammatory cytokines, chemokines and antibiotic peptides including IL-36γ, CXCL1, CXCL2, CCL20, S100A7, S100A8 and S100A9, which are closely related to the pathogenesis of psoriasis." (PMID 32194991, 2020). "Calgranulins S100A8 and S100A9 are markers of keratinocyte activation and have been demonstrated to play a role in hyper-proliferation and abnormal differentiation of keratinocytes in psoriasis and also result in the development of severe crusted lesions in sheep scab." (PMID 32886659, 2020). "We suggest that ANGPTL6-dependent mechanisms associated with psoriasis may be independent of those governed by S100A9." (PMID 27698489, 2016). "Thus, S100A9 loss in K14-Angptl6 Tg male or female mice did not rescue psoriasis-like skin phenotypes, suggesting that ANGPTL6-dependent psoriasis emerges independently of S100A9 and that these phenotypes are not sex-dependent." (PMID 27698489, 2016). "In all five mouse phenotypes, there was increased expression of S100a9, Lcn2, S100a8, Sprr1b, Mpzl2, Has3, as well as decreased expression of Tppp, Stxbp6, and Cldn23, and each of these effects is consistent with characteristic expression patterns in clinical psoriasis." (PMID 21483750, 2011).
psoriasis (continued). "A few inflammatory genes that were shared with vulvar lichen sclerosis and psoriasis were S100A8, S100A9 and FABP5." (PMID 41438752, 2025). "Research has indicated that S100A8 and S100A9 are highly expressed in autoimmune diseases such as Rheumatoid Arthritis (RA), Systemic Lupus Erythematosus (SLE), Psoriasis (Pa) and Juvenile Idiopathic Arthritis (SoJIA)." (PMID 39877611, 2025). "Notably, S100A9 monomers can have anti-inflammatory effects, such as suppressing macrophage activation, and calprotectin tetramers may reduce inflammation in diseases like psoriasis and arthritis." (PMID 40874857, 2025). "To further investigate the role of SLPI, S100A9, IL1B, CYBB, CXCL8, S100A12, and CXCL1 genes in the immune microenvironment of psoriasis, we examined inflammatory cell infiltration." (PMID 39014096, 2024). "In psoriasis, S100A7, S100A8, S100A9, S100A12, and S100A5, defined as “antimicrobial peptides”, are the main S100 family members involved." (PMID 38255845, 2024). "The PPI results and friends analysis demonstrated strong correlations between S100A9, S100A8, NAMPT, TYMP and others, suggesting their potential involvement in the regulation of PANoptosis in psoriasis." (PMID 39480805, 2024). "To identify potential therapeutic options for psoriasis and AMI, we screened drugs targeting CXCL8, IL1B, S100A9, and S100A12 using the DsigDB database." (PMID 39014096, 2024). "In psoriasis-affected tissues, S100A8 and S100A9 are highly expressed in the basal and spinous layers." (PMID 37891988, 2023). "The expression levels of several S100 proteins, such as S100A2, S100A7, S100A8/S100A9, S100A12, and S100A15, are significantly up-regulated in psoriasis-involved skin." (PMID 37346040, 2023). "The DEGs between IL-17A treated STAT3 mice and WT mice were highly consistent with those observed in psoriasis patients, including S100A8, S100A9, Sprr2, and LCE." (PMID 37465147, 2023). "When comparing psoriasis-involved skin to the adjacent normal skin of patients with psoriasis, differentially methylated CpGs are found, some of which situated at the promoters of known PSORS genes, such as S100A9, PTPN22, SELENBP1, CARD14, and KAZN." (PMID 37628670, 2023). "Among these proteins, well-known circulating markers for psoriasis such as P-selectin (P16109), S100A8 (P05109), S100A9 (P06702), and talin-1 (Q9Y490) were found to be upregulated in patients with psoriasis compared to healthy control." (PMID 36804462, 2023). "It induces the expression of other psoriasis signature genes, such as IL36G, S100A15, DEFB4A, S100A9, CXCL8, TNIP3 (coding TNF-α-induced-protein 3 or TNFAIP3), and LCN2 (by synergy of IL-17C with TNF-α) in keratinocytes." (PMID 36928592, 2023). "In support of the Role of IL-17A in the Psoriasis Pathway, CXCL1, CXCL3, CXCL6, S100A8, S100A9, and CCL20 in the shared signature were all upregulated in both psoriatic skin and colon lesional tissues." (PMID 36396672, 2022). "A series of psoriasis-related genes, such as S100A8, S100A9, KRT6A (keratin 6A), KRT6B, KRT6C, KRT16, and MMP9 (metalloproteinase 9), were also down-regulated." (PMID 35273606, 2022). "Some of these transcripts encode proteins that have been proposed as potential biomarkers for intra-amniotic infection or inflammation in women with preterm labor, such as ENSECAG00000008686 (psoriasis; S100A7) and ENSECAG00000010615 (calgranulin B; S100A9)." (PMID 34238364, 2021). "Psoriasis-related genes in HaCaT cells, such as S100A7, S100A8, and S100A9, were downregulated by miR-193b-3p overexpression in the presence or absence of M5 treatment." (PMID 34667159, 2021). "High abundance of these S100-proteins during psoriasis can be explained especially by the effects of IL-17A, IL-17F, TNF, and IL-1α on S100A8/S100A9 expression, which are all central players in the pathogenesis of psoriasis." (PMID 33643287, 2020).
psoriasis (continued). "S100A7 (psoriasin), S100A8 (calgranulin A), S100A9 (calgranulin B), S100A12 (calgranulin C), and S100A15 are highly expressed in psoriasis." (PMID 33050592, 2020). "In particular, the host employs S100 family proteins, such as S100A7 protein psoriasis secreted by keratinocytes and S100A8/S100A9 dimer calprotectin secreted by neutrophil granulocytes to sequester zinc locally and extracellularly." (PMID 33028391, 2020). "Throughout inflammatory dermatoses, especially in psoriasis, both S100A8 and S100A9 are highly up-regulated in skin lesions of patients." (PMID 33643287, 2020). "Previous genomic transcriptome studies on the effect of NB-UVB in psoriasis showed downregulation of S100A8 and S100A9 in response to NB-UVB." (PMID 30865695, 2019). "S100A8 and S100A9 are antimicrobial peptides that form a heterodimer called calprotectin which interacts with Toll-like receptor 4 (TLR-4) and exacerbates psoriasis by activating complement factor C3 and recruiting neutrophils." (PMID 30279326, 2018). "S100A7 (psoriasin), S100A8 (calgranulin A), S100A9 (calgranulin B), and S100A12 (calgranulin C) are markedly increased in psoriasis lesions." (PMID 29619128, 2018). "Psoriasin, S100A8 (calgranulin A) and S100A9 (calgranulin B) are expressed in ductal carcinoma in situ (DCIS), as well as in the hyperproliferative skin disease, psoriasis." (PMID 17986321, 2007). "Additionally, we explored the skin lesions of psoriasis patients and found significantly higher expression of CXCL8, IL-1B, S100A9, and S100A12 in the affected skin areas compared to unaffected regions." (PMID 39014096, 2024). "The transcriptional expressions of Cxcl1, Cxcl2, Il-1β, Il-1α, S100A8, S100A9, Il-6, and Vegf were significantly decreased in skin lesions of K14.Bsgfl/fl mice, indicating the proinflammatory role of the epidermal expression of CD147 in psoriasis." (PMID 37303600, 2023). "A recent study has shown that disruption of the epidermal barrier can exacerbate psoriasis by unregulated keratinocyte proliferation and the overexpression of S100A8, S100A9, CXCL1, and other molecules, indicating a defect in ceramide-dependent epidermal barrier signaling and function." (PMID 36837912, 2023). "Our data indicate that expression of S100A8 and S100A9 does not primarily influence maturation or activation of keratinocytes but rather represents the inflammatory response of these cells during psoriasis." (PMID 33643287, 2020). "Some studies have shown decreased levels of IL-17A, TNF-α, S100A15, S100A7, S100A9 and IL-6 gene expression in PBMCs after NB-UVB treatment in patients with psoriasis whereas other pro-inflammatory mediators such as sVCAM-1, sICAM-1, sE-selectin, MMP-9, and MPO showed no significant reduction." (PMID 30865695, 2019). "Notably, the “Role of IL-17A in Psoriasis” (T2, −log(FDR) = 1.67) pathway was enriched, in which downregulated CXCL3, IL-8, S100A8, S100A9, IL17RA and CXCL1 expression was observed." (PMID 29871627, 2018). "For example, S100A4 is involved in autoimmune pancreatitis, S100A11, S100A8 and S100A9 in rheumatoid arthritis, S100A1 in hypoxia-induced inflammatory response in cardiomyocytes, S100A12 in Crohn’s disease, S100A7 and S100A7A in psoriasis, S100A8, S100A9 and S100A12 in systemic lupus erythematosus." (PMID 30018736, 2018). "Psoriasis-like skin phenotypes exhibited by mice mutant in S100A9 were not rescued on a K14-Angptl6 Tg background." (PMID 27698489, 2016). "Levels of the proteins S100A9, recently proposed as therapeutic targets for psoriasis, also increased in skin tissue of K14-Angptl6 Tg mice, but psoriasis-like inflammatory phenotypes in those mice were not rescued by S100A9 deletion." (PMID 27698489, 2016). "All other DEGPs could be placed along a continuum, with some showing greater psoriasis specificity (e.g., DBI, GLTP, HRNR, KRT73, ELOVL7), and others showing similar expression shifts in many or most skin diseases (e.g., MX1, S100A8, S100A9, STAT1, LAP3)." (PMID 26251673, 2015).
psoriasis (continued). "Interestingly, several genes with major relevance in psoriasis have been found differentially expressed as a consequence of NAC treatment in the particular epithelial cells included in this study, for example S100A9, ID-1 and Cox-2." (PMID 16001974, 2005). "Immunohistochemical, western blot, and multiplex analysis showed that the TLR activation induced the expression of psoriasis associated markers like S100A7, p-STAT3, CXCL-1, IL-8, IL-1α, S100A9, and IL-23 in the wild type but not in the TLR KO epidermis models." (PMID 40995100, 2025). "Furthermore, the relevance of the feedback between TNF-α and S100-proteins has been confirmed for inflammatory processes like arthritis and psoriasis and IL-6 is the top cytokine induced by S100A8/S100A9 in myeloid cells as shown in a genome wide transcriptome analysis." (PMID 37056775, 2023). "Interestingly, S100A8, S100A9 and S100A12 protein levels are used as sensitive biomarkers for monitoring disease activity in juvenile idiopathic arthritis, inflammatory bowel disease and psoriasis." (PMID 35055093, 2022). "However, the specific role of S100A8/S100A9 expression in keratinocytes during the process of psoriasis has never been addressed." (PMID 33643287, 2020). "However, looking on the effects of cytokines highly relevant in the pathogenesis of psoriasis, i.e., IL-17A, IL-17F, IL-1α, or TNF, on S100A8 or S100A9 expression in keratinocytes we found strong effects on mRNA induction for both genes most pronounced for IL-17A > IL-17F > IL-1α > TNF." (PMID 33643287, 2020). "Twenty-one S100 proteins are known, of which S100A7 (psoriasin), S100A8 (calgranulin A), S100A9 (calgranulin B), S100A12 (calgranulin C), and S100A15 have antimicrobial effects and their expression levels are increased in the lesional skin and serum of psoriasis patients." (PMID 32947991, 2020). "Interestingly, psoriasis-like skin proliferative and inflammatory phenotypes were not rescued in K14-Angptl6 Tg mice by S100A9 deletion." (PMID 27698489, 2016). "By contrast, S100A8 and S100A9 proteins were abundant in skin tissues of all 15 psoriasis patients but not in tissues from any non-psoriasis control subject, suggesting that ANGPTL6 production and S100A8/S100A9 expression are not linked in the pathogenesis of psoriasis." (PMID 27698489, 2016). "In recent studies comparing psoriasis-involved skin to adjacent non-lesional skin, differences in CpG methylation were found at the promoters of known PSORS genes, such as S100A9, PTPN22, SELENBP1, CARD14, and KAZN." (PMID 38256115, 2024). "In addition, the expression of psoriasis-related inflammatory response markers, including Keratin 16, S100A8, and S100A9, was not reduced by anti-FGFR2IIIb treatment." (PMID 39919800, 2025).